ST3GAL5 (ST3 beta-galactoside alpha-2,3-sialyltransferase 5)
Description:
Transfers the sialyl group (N-acetyl-alpha-neuraminyl or NeuAc) from CMP-NeuAc to the non-reducing terminal galactose (Gal) of glycosphingolipids forming gangliosides (important molecules involved in the regulation of multiple cellular processes, including cell proliferation and differentiation, apoptosis, embryogenesis, development, and oncogenesis). Mainly involved in the biosynthesis of ganglioside GM3 but can also use different glycolipids as substrate acceptors such as D-galactosylceramide (GalCer), asialo-GM2 (GA2) and asialo-GM1 (GA1), although less preferentially than beta-D-Gal-(1->4)-beta-D-Glc-(1<->1)- Cer (LacCer).
Synonyms: ST3GalV; SIAT9; SIATGM3S; SATI; SPDRS; ST3Gal V
Tractability: Antibody: UniProt predicts a signal peptide or a membrane-spanning region. PROTAC: its protein half-life has been measured.
Gene: Protein-coding gene on chromosome 2 (85,837,120 to 85,905,199, reverse strand). Ensembl gene ENSG00000115525.
Subcellular location: Golgi apparatus membrane
Subcellular location (Human Protein Atlas): Vesicles
Pathways (Reactome):
Metabolism: Glycosphingolipid biosynthesis
Metabolism of proteins: Sialic acid metabolism
Gene Ontology:
Molecular function: lactosylceramide alpha-2,3-sialyltransferase activity; beta-galactoside (CMP) alpha-2,3-sialyltransferase activity; sialyltransferase activity
Biological process: ganglioside biosynthetic process; glycoprotein biosynthetic process; glycosphingolipid biosynthetic process
Cellular component: Golgi membrane; membrane
Genetic constraint (gnomAD): Loss-of-function variants: 22 observed, 42.69 expected, observed/expected ratio (o/e) 0.52, 90% interval 0.37 to 0.74. The upper end of that interval is the gene's LOEUF score, 0.74, which puts it in group 3 of 6, group 1 being the genes least tolerant of losing a copy. Missense variants: 422 observed, 513.28 expected, observed/expected ratio (o/e) 0.82, 90% interval 0.76 to 0.89. Synonymous variants: 178 observed, 185.35 expected, observed/expected ratio (o/e) 0.96, 90% interval 0.85 to 1.09.
Gene-disease validity (ClinGen):
ClinGen rates the evidence that ST3GAL5 causes each of these diseases.
GM3 synthase deficiency (autosomal recessive): Definitive. GM3 synthase deficiency is characterized by recurrent seizures (epilepsy) and problems with brain development.
Homologues: Orthologues: macaque ST3GAL5 (98% identical), chimpanzee ST3GAL5 (93% identical), dog ST3GAL5 (92% identical), pig ST3GAL5 (90% identical), rabbit ST3GAL5 (87% identical), mouse St3gal5 (83% identical), guinea pig ST3GAL5 (78% identical), rat St3gal5 (78% identical), tropical clawed frog st3gal5 (50% identical), zebrafish st3gal5 (38% identical). Paralogues in human: ST3GAL3 (32% identical), ST3GAL4 (26% identical), ST3GAL6 (23% identical), ST6GAL2 (19% identical), ST6GALNAC1 (18% identical), ST3GAL1 (17% identical), ST3GAL2 (17% identical), ST6GALNAC2 (17% identical), ST6GAL1 (16% identical), ST6GALNAC4 (13% identical), ST6GALNAC6 (13% identical), ST6GALNAC5 (12% identical), and 2 more.
Diseases named in the same sentence as ST3GAL5 in open-access papers:
ST3GAL5 is named in the same sentence as 72 diseases in open-access papers, as found by Europe PMC text mining. Sharing a sentence is not in itself a finding about the gene and the disease. The quoted sentences say what the papers report.
infantile-onset symptomatic epilepsy syndrome (13 papers, 2013 to 2025). "Patients carrying a rare mutation in the ST3GAL5 gene develop infantile onset symptomatic epilepsy syndrome (West syndrome), dyspigmentation of the skin, and abnormal auditory responses." (PMID 41044357, 2025). "GM3 synthase deficiency (GM3SD) is an autosomal recessive disorder resulting from mutations in the ST3GAL5 gene." (PMID 39533347, 2024). "GM3 synthase deficiency (GM3SD) is an infantile-onset epileptic encephalopathy syndrome caused by biallelic loss-of-function mutations in ST3GAL5." (PMID 37014712, 2023). "In humans, mutations in the ganglioside-specific sialyltransferase ST3Gal5 (GM3 synthase) gene cause: infantile-onset epilepsy syndrome and salt and pepper syndrome, with severe intellectual disability." (PMID 32581723, 2020). "In particular the deficiency of ST3GAL5 (GM3 synthase) causes Amish infantile epilepsy syndrome (OMIM 609056), an autosomal recessive syndrome associated with developmental stagnation and blindness." (PMID 30088207, 2018). "Mutations in the ST3GAL5 gene, encoding for the GM3-synthase, result in an early-onset seizure disorder, also known as the salt and pepper syndrome, characterized by motor and cognitive disturbances." (PMID 35884824, 2022). "LacCer is the only known substrate for ST3Gal V activity and a loss-of-function mutation in ST3GAL5 gene is associated with the infantile-onset symptomatic epilepsy syndrome." (PMID 24709879, 2013).
epilepsy (9 papers, 2018 to 2023). A brain disorder characterized by episodes of abnormally increased neuronal discharge resulting in transient episodes of sensory or motor neurological dysfunction, or psychic dysfunction. "Pathogenic variants in CNTN2 and ST3GAL5 are associated with myoclonic epilepsy and epilepsy, respectively." (PMID 34816733, 2021). "As ST3GAL5 dysfunction causes epilepsy and altered electrical cortical activity, we also evaluated the electroencephalography (EEG) in the mutant animals." (PMID 34944404, 2021). "For example, mutations in the ST3Gal5 gene that encodes monosialoganglioside GM3 synthase have been linked to infant onset epilepsy, while mutations in the ST3Gal5 and B4GalNT1 genes, which encode GM2 synthase, increase the risk of developing multiple sclerosis." (PMID 38235387, 2023). "Since severe epilepsy is associated with defects in ganglioside synthesis in humans, and audiogenic seizures are a feature of St3gal5-null mice, the question arises whether changes in brain ganglioside levels could underlie or contribute to other forms of epilepsy." (PMID 33117120, 2020). "ST3GAL5 (ST3 Beta-Galactoside Alpha-2,3-Sialyltransferase 5): Salt and pepper developmental regression syndrome (epilepsy, abnormal brain development and intellectual disability)." (PMID 31031802, 2019). "A deficiency in GM3-derived gangliosides, resulting from a lack of lactosylceramide-alpha-2,3-sialyltransferase (ST3GAL5), leads to severe neuropathology, including epilepsy and metabolic abnormalities." (PMID 34944404, 2021).
bladder cancer (8 papers, 2017 to 2025). "Following the same rationale, stable transfection of murine bladder carcinoma cells with cDNA encoding human GM3 synthase (ST3GAL5) resulted in reduced tumor proliferation, motility, and invasion while promoting apoptosis and suppressing xenograft tumor growth." (PMID 40252176, 2025). "A study analyzing gene-expression data from bladder cancer patients revealed that ST3GAL5 expression significantly modulates the tumor immune microenvironment." (PMID 40252176, 2025). "In vivo, upregulation of ST3GAL5 significantly inhibited the tumorigenicity of bladder cancer cells subcutaneously inoculated into BALB/c nude mice." (PMID 40252176, 2025). "Though ST3GAL5 overexpression is required for breast cancer stemness, its downregulation leads to muscle invasion and a worse prognosis in bladder cancer patients, suggesting that the role of ST3GAL5 is cellular context-dependent." (PMID 36092699, 2022). "Additionally, a recent study showed that a low expression level of ST3GAL5 correlates with increased tumorigenesis and progression of bladder cancer, highlighting its potential as a predictive biomarker as well as a therapeutic target." (PMID 40252176, 2025). "Similar to the cancer type-dependent role of ST3GAL5, ST3GAL6 is upregulated in liver cancer and multiple myeloma, as well as the basal subtype of bladder cancer, but downregulated in colorectal cancer." (PMID 36092699, 2022). "ST3GAL5 (also called GM3 synthase) is downregulated in tumor tissues compared to adjacent normal bladder tissues, with its expression levels higher in low-grade tumors than in high-grade bladder cancer." (PMID 40252176, 2025). "Ultimately, strategies involving ST3GAL5 and ST8SIA1 overexpression, or inhibition of ST3GAL6, FUT4 and FUT7, could offer new therapeutic avenues for bladder cancer." (PMID 40252176, 2025). "Hence, it is not surprising that the downregulation of ST3GAL5 was reported in bladder cancer." (PMID 36172374, 2022).
breast carcinoma (8 papers, 2008 to 2024). "For instance, silencing ST3Gal5 in murine breast cancer cells resulted in reduced cell migration and invasion in vitro, and led to a reduction in lung metastasis in vivo." (PMID 38785323, 2024). "Increased mRNA expression of ST3GAL2, as well as ST3GAL5 and ST8SIA1, was also observed in breast cancer stem cells which is eventually linked to increased expression of gangliosides in these cells." (PMID 34975914, 2021). "Ganglioside GD2 was also identified as a putative marker of CD44hiCD24lo breast cancer stem cells (CSC) capable of initiating tumors, and several GT genes involved in GD2 biosynthesis (ST3GAL5, B4GALNT1, and ST8SIA1) are highly expressed in CSC." (PMID 29698439, 2018).
melanoma (7 papers, 2014 to 2025). A malignant, usually aggressive tumor composed of atypical, neoplastic melanocytes. "We used lipidomics, CRISPR/Cas9 knockout screening, molecular and biophysical experiments, followed by xenograft melanoma animal studies to demonstrate that gomesins target the glycosphingolipid pathway via inhibition of the ST3GAL5 gene." (PMID 41271646, 2025). "Therefore, we followed up by using shRNA knock-down in melanoma cells to target the hits identified from our CRISPR KO screen (ST3GAL5, B4GALT5, UGCG, p < 0.05, FDR < 0.2)." (PMID 41271646, 2025). "To predict the prognosis of melanoma patients, we calculated the risk score of each patient based on the expression and corresponding lambda value of seven genes (PLA2G2D, FUT8, PLA2G4E, PLA2G5, PLA2G1B, B3GNT2, and ST3GAL5)." (PMID 37205993, 2023). "We selected the best candidate from a battery of shRNAs for each of these genes and confirmed through viability assay that individually knocking down ST3GAL5, B4GALT5 or UGCG diminished the cytotoxicity of both AgGom and HiGom in melanoma cells." (PMID 41271646, 2025). "RNA-sequencing data from the TCGA melanoma database revealed that the sialyltransferases ST3GAL5, ST6GALNAC2 and ST3GAL6 are consistently expressed in the investigated melanoma samples." (PMID 34440905, 2021). "However, 7,8-DHF did not suppress ST3GAL5 and ST8SIA1 mRNA expression in SK-MEL-2 or G-361 melanoma cells." (PMID 36991237, 2023).
Intellectual disability (5 papers, 2019 to 2024). "ST3GAL5 mutations cause an autosomal recessive form of severe infantile-onset neurological disease characterized by progressive microcephaly, intellectual disability, dyskinetic movements, blindness, deafness, intractable seizures, and pigment changes." (PMID 35628171, 2022). "Mutations in the ST3GAL5 gene leading to GM3 synthase deficiency result in severe phenotypes, including intellectual disability, developmental stagnation, microcephaly, hearing impairment, and visual impairment." (PMID 39533347, 2024).
hepatocellular carcinoma (4 papers, 2020 to 2024). A malignant tumor that arises from hepatocytes. "Overexpression of ST3GAL5 significantly promoted the proliferation and invasion of hepatoma cells." (PMID 31998783, 2020). "In contrast, knockdown of ST3GAL5 inhibited proliferation and metastasis of hepatoma cells." (PMID 31998783, 2020). "In hepatocellular carcinoma (HCC) cell lines, the tumor suppressors miR-26a, miR-548l and miR-34a have been shown to negatively regulate the expression of ST3GAL5." (PMID 33921986, 2021). "However, in hepatocellular carcinoma (HCC), miR-26a, miR-548l, and miR-34a suppress tumor growth by targeting the ST3GAL5 gene." (PMID 34084160, 2021).
Insulin resistance (4 papers, 2015 to 2025). Increased resistance towards insulin, that is, diminished effectiveness of insulin in reducing blood glucose levels. "In omental adipose tissue of obese, insulin-resistant women, increased GM3 levels and the corresponding sialyltransferase ST3GAL5 were associated with adipocyte hypertrophy, macrophage infiltration, and inflammation." (PMID 41301440, 2025). "Insulin resistance in adipocytes induced by TNFα is accompanied by an increased GM3 biosynthesis through the up-regulation of GM3 synthase (ST3GAL5) gene expression." (PMID 25955839, 2015). "Studies have shown that increased gene expression of ST3GAL5 and GM3 levels in adipose tissue and serum correlate with insulin resistance, especially in obese and diabetic conditions." (PMID 41301440, 2025). "In obesity, leptin and insulin resistance are accompanied by increased levels of GM3 synthase in animal and human studies; the genetic deletion of ST3GAL5 has rescued insulin resistance in mice fed with a high-fat diet." (PMID 34944404, 2021).
acute myeloid leukemia (3 papers, 2017 to 2023). Acute myeloid leukemia (AML) is a group of neoplasms arising from precursor cells committed to the myeloid cell-line differentiation. "In addition, ST3GAL5 has been reported to be positively associated with high risk of childhood acute leukemia and is associated with multidrug resistance in human acute myeloid leukemia, indicating the role of ST3GAL5 in cancer development and progression." (PMID 31998783, 2020). "Another gene, ST3GAL5, has been reported to be positively correlates with the high risk of pediatric acute leukemia and associated with multidrug resistance in human acute myeloid leukemia, indicating the function of ST3GAL5 in carcinogenesis and development." (PMID 28977887, 2017). "With respect to Sia modifications, prior studies have reported a positive correlation between Sialyl transferases, ST3Gal5 and ST8Sia4 expression and efflux proteins, PgP and MRP1 expression in human acute myeloid leukemia." (PMID 37377914, 2023).
Blindness (3 papers, 2018 to 2022). Blindness is the condition of lacking visual perception defined as a profound reduction in visual perception. "In humans, the GM3 synthase ST3GAL5 is associated with severe infantile-onset seizures, developmental delay, and blindness." (PMID 32084196, 2020).
colorectal cancer (3 papers, 2022 to 2024). A primary or metastatic malignant neoplasm that affects the colon or rectum. "In this paper we investigated the role of ST3Gal5 and thereby the modulation of the ganglioside biosynthesis on the anti-tumor immune response and on angiogenesis in colorectal cancer, by modifying its expression on tumor cells." (PMID 38785323, 2024).
developmental delay (3 papers, 2020 to 2024). "Genetic deficiency of sialyltransferase ST3GAL3 (OMIM#611090) and ST3GAL5 (OMIM#609056), two enzymes that add sialic acid residues to glycoproteins and glycolipids, leads to infantile epilepsy and developmental delay." (PMID 34163424, 2021).
Spastic paraplegia (3 papers, 2019 to 2023). Complete loss of the ability to move the lower limbs accompanied by spasticity of the lower limbs. "Several glycosyltransferase genes involved in ganglioside synthesis were found to be significantly upregulated, including GM3 synthase (St3gal5) and GM2 synthase (B4galnt1), a lack of which has been linked to hereditary epilepsy and spastic paraplegia, respectively." (PMID 31887977, 2019).
deafness (2 papers, 2021 to 2022). An inherited or acquired condition characterized by the complete loss of the ability to hear from one or both ears. "Furthermore, the changes in these measures were different in the male and female St3gal5−/− mice, which display no sex difference in the development of deafness." (PMID 34944404, 2021).
epilepsy syndrome (2 papers, 2020 to 2022). A syndrome that has a characteristic cluster of clinical features and/or lectroencephalographic (EEG) findings that reflect underlying epileptic activity. "Mutations in ST3GAL5, encoding GM3 synthase, which initiates the synthesis of all downstream cerebral gangliosides, result in an extremely severe epilepsy syndrome." (PMID 34757540, 2022).
liver cancer (2 papers, 2020 to 2022). An epithelial or non-epithelial malignant neoplasm that arises from the liver. "This indicates that ST3GAL5 is closely related to the invasion and metastasis of liver cancer." (PMID 31998783, 2020).
neuroblastoma (2 papers, 2018 to 2023). Neuroblastoma (NB) is the most common solid, extracranial childhood tumor. "hsa-miR-34a has been reported to regulate ALG13, FUT8, GALNT7, and ST3GAL5 in neuroblastoma and hepatocellular carcinoma." (PMID 37188790, 2023).
ovarian carcinoma (2 papers, 2017). A malignant neoplasm originating from the surface ovarian epithelium. "The additional profiling of other sialyltransferase genes, ST6GAL2, ST3GAL4 and ST3GAL5, was found to display varying gene expression levels between both cancer tissue types and across all tested ovarian cancer cell lines." (PMID 28853212, 2017). "In addition, KLF4 was identified as a putative upstream regulator of drug resistance in ovarian cancer and together with ST3GAL5, SYNE1, CXCL8, HERC5, FOSL1, ARRDC4 merits further studies." (PMID 28473707, 2017).
Age-related cataract (1 paper, 2024). A type of cataract (opacification of the lens) that forms during the course of aging. "Implications for future research and clinical applications may include alternative treatment of age-related cataract such as solid lipid nanoparticles to target certain proteins, like GLA and ST3GAL5, in order to slow down or even prevent age-related cataract progression." (PMID 39685745, 2024).
Anxiety (1 paper, 2021). Intense feelings of nervousness, tension, or panic often arise in response to interpersonal stresses. "We found that St3gal5−/− mice exhibit locomotor hyperactivity, impulsivity, neophobia, and anxiety-like behavior." (PMID 34944404, 2021). "The St3gal5−/− genotype also decreased the time spent in central zone of open field and in the open arms of elevated plus maze (p < 0.05), which is suggestive of increased anxiety." (PMID 34944404, 2021).
brain tumor (1 paper, 2018). "PLEKHA5 facilitates cell migration and invasion and is linked to brain tumor metastasis via the PI3K-AKT pathway, whereas ST3GAL5 encodes a sialyltransferase that catalyzes the formation of ganglioside GM3, a suppressor of EGFR/PI3K-AKT signaling and cell proliferation, and a inducer of apoptosis." (PMID 29587824, 2018).
Choreoathetosis (1 paper, 2019). Involuntary movements characterized by both athetosis (inability to sustain muscles in a fixed position) and chorea (widespread jerky arrhythmic movements). "Mutations in the ST3GAL5 gene, which encodes the first sialyltransferase (GM3 synthase) in the ganglioside biosynthetic pathway, cause an early-onset epilepsy syndrome with severely delayed motor and cognitive development and choreoathetosis." (PMID 31447771, 2019).
cystic kidney (1 paper, 2020). "One example in the context of kidney disease is the cross breeding of ST3Gal5 knockouts with a transgenic mouse line bearing the juvenile cystic kidney mutation (jck), responsible for polycystic kidney." (PMID 33348903, 2020).
depression (1 paper, 2012). "The 15 target genes include DYNLT1, GCH1, TOR1B, DISC1, MEF2A and ST3GAL5 that to date were never related to an IFN-α regulation while all of them have been described in association with brain development or depression." (PMID 22701688, 2012).
diabetic nephropathy (1 paper, 2023). "Here, we analyzed the therapeutic effects of enhanced GM3 via VPA-induced activation of St3gal5 on albuminuria and podocyte injury in streptozotocin (STZ)-induced diabetic nephropathy model mice." (PMID 37511118, 2023). "Therefore, in this study, our results indicated that the observed inhibition of mesangial cell expansion in diabetic nephropathy mice treated with VPA may not be due to the activating effect of VPA on the GM3 synthase gene (St3gal5)." (PMID 37511118, 2023).